AR (androgen receptor)
Diseases named in the same sentence as AR in open-access papers (continued):
Sharing a sentence is not in itself a finding about the gene and the disease.
cancer (continued). "Therefore, identification of AR-target proteins that are also overexpressed in the cancer SC population would be an attractive therapeutic approach." (PMID 25965834, 2015). "Androgen action and cell cycle progression has been examined in AR-immunoreactive cancer cells." (PMID 26372468, 2015). "Furthermore, it has a binding site for androgen receptor (AR) and acts as a co-regulator to suppress androgen-AR transactivation function in prostrate cancer cells." (PMID 25873625, 2015). "Especially, the expression of both DBC1 and AR predicted shorter survival of cancer patients." (PMID 25823848, 2015). "To confirm whether the observed anti-cancer effects of VNLG-152 on PCa cells was primarily due to its inhibitory effects on AR and MNK, we investigated the impact of AR and/or MNK siRNA on the survival of LNCaP cells by MTT assay." (PMID 25605250, 2015). "The effects of AR activity on disease progression vary depending on cancer type." (PMID 26397136, 2015). "We next dichotomized the cohort by median AR level in cancer epithelia or cancer stroma." (PMID 25965833, 2015). "Interestingly, the cells under hypoxia condition showed lower expressions of AR downstream genes, while also showing higher expression of the cancer stem cell also markers." (PMID 26342197, 2015). "Taken together, our data suggest that AR-agonists at supraphysiological levels mediate induction of cellular senescence in human PCa cells, which may have a protective anti-cancer role." (PMID 25216853, 2014). "Since FKBP5 represents a scaffold protein and the AR is upregulated in tumors and chemoresistant cancer cells, we examined the possibility that these proteins may interact." (PMID 25460502, 2014). "Recently, AR was found to induce cancer cell adhesion and survival through integrin expression." (PMID 25200184, 2014). "Our understanding of the role of the RANKL/RANK and AR axes in cancer cell adhesion is evolving." (PMID 25200184, 2014). "Thus, the present finding showing that AR can regulate L1CAM in a direct fashion adds a novel element to the complex regulation of L1CAM in cancer." (PMID 25510351, 2014). "Both GAK and AR localized to the nuclei of cancer cells in GAK-positive surgical specimens." (PMID 24971999, 2014). "Our findings imply that under physiological settings of ADT, a long-term shift in the Nrf1 and Nrf2 balance in cancer cells may result in enhanced AR function in a subpopulation of cells and enable the outgrowth of CRPC." (PMID 24466341, 2014). "In contrast to recent data from Thike and colleagues, AR status did not modify Core Basal patient prognosis, suggesting that a multi-Institutional series of cases with definition of TNBC subtypes should further investigate implications of AR deregulation n in this specific cancer subset." (PMID 24505496, 2014). "The signal from TGFβ, via the AR, played a critical role in the deregulation of TGFβ signaling in prostate and/or liver tumorigenesis, and those TGFβ effectors (Smads 3 and 4) serving as negative regulators of AR-mediated transcription in cancer cells have been established by several investigations." (PMID 24949437, 2014). "Thus, AR mediates growth suppression by specifically targeting Ras-driven growth-promoting pathways, highlighting the role of androgen/AR axis in human cancers." (PMID 25646090, 2014). "Previously, we showed that CDK11p58 interacts with AR in the postate cancer cell lines." (PMID 24397471, 2014). "The potential role of non-genomic signaling activated by androgen/AR axis in cancer-associated fibroblasts (CAFs) is also discussed." (PMID 25646090, 2014). "Since PCa is androgen-dependent, the first aim of the present study was to examine whether insulin or glucose levels had any effect on the androgen receptor (AR) in PCa LNCaP cells (an androgen-sensitive immortalized PCa cancer cell line)." (PMID 24058525, 2013).
cancer (continued). "Therefore, it is conceivable that EGF/AR crosstalk plays a role in cancer development, when androgen levels decline as a consequence of ageing or pathological conditions." (PMID 24130806, 2013). "The increased level of ABCG2 in BFTC cells overexpressing AR may explain their higher viability under anti-cancer drug treatment." (PMID 23599788, 2013). "To validate this hypothesis, we combined the gene expression profiling, pathway analysis, and gene promoter analysis to identify AR-target genes differentially expressed between AA and CA cancer specimens." (PMID 23365759, 2013). "This would enable cancer cells to support aberrant growth promoting signalling and AR activity." (PMID 23724116, 2013). "Our genomic findings support this notion of AR signaling in cancer health disparities, and advance the hypothesis that an overall generalized augmentation of AR signaling components has occurred in AA PCa." (PMID 23365759, 2013). "AR-independent pathway, which is beyond the scope of this review, includes AR-independent activation of survival or anti-apoptotic pathway and mechanisms involving subpopulation of intrinsically AR-independent cancer cells." (PMID 23896594, 2013). "Taken together, these results suggest that differential expression of AR-target genes may contribute to the more aggressive cancer phenotype (e.g., cell proliferation, antiapoptosis, invasiveness, and angiogenesis) reported in AA PCa." (PMID 23365759, 2013). "The strong stimulation of GNMT by androgen together with the detection of its expression in AR-positive cancer cell lines and its inhibition upon AR knockdown indicated that AR may directly regulate GNMT expression." (PMID 23997240, 2013). "Thus, the HT1080 cell line represents a new model of hormone-responsive cancer cells useful to dissect the role of androgen signaling independently of AR transcriptional activity." (PMID 24130806, 2013). "Moreover, it has been shown to reduce Myc, AR and Erg levels, to inhibit nuclear factor-κB activity and to trigger oxidative stress in this type of cancer." (PMID 24278179, 2013). "Various untransformed and cancer-derived cell types express both AR and EGFR." (PMID 24130806, 2013). "Results obtained using reproductive and non-reproductive cells, untransformed cells (fibroblasts) or cells derived from different human cancers (prostate, breast, colon and pancreas) indicate that AR blockade by Casodex impairs EGF-elicited biological responses in these cells." (PMID 24130806, 2013). "Moreover, SFN inhibits multiple oncogenic signaling pathways often hyperactive in human cancers, including nuclear factor-κB, Akt, signal transducer and activator of transcription 3, and androgen receptor." (PMID 22970326, 2012). "Sub-GSE is able to identify numerous cancers in which the Androgen receptor pathway is perturbed." (PMID 22536907, 2012). "Seven pathways, including the Androgen receptor, Hedgehog, IL-1, IL-5, IL-9, Notch, and Wnt signaling pathways were not significantly perturbed by any condition in our dataset, leaving 13 pathways that were perturbed by at least one cancer." (PMID 22536907, 2012). "Here, we for the first time link AR anti-cancer action with cell senescence in vitro and in vivo." (PMID 22403609, 2012). "Alternatively, AR signalling may remain active at early stages of transformation but become repressed as the cancer cells eventually progress into an AR-independent status." (PMID 21241512, 2011). "AR was shown to activate the transcriptional program of a distinct set of gene networks, including many genes involved in cell cycle regulation, during progression of the cancer cells to androgen independence." (PMID 21276246, 2011). "Although HH/GLI1 signalling modulates CSC biology in various tissues, defining itsrole in PCa is complicated by the fact that cancer-initiating cells may stem fromAR− (basal) or AR+ (intermediate/luminal)populations." (PMID 21633508, 2011).
cancer (continued). "Androgen and AR could promote Bax-mediated apoptosis; however, down-regulation of AR by synthetic or natural agents could also induce apoptosis and inhibit cancer cell proliferation." (PMID 22200028, 2011). "Elucidating the specific mechanisms involved in the competition between Pax6 and SPBP for binding to AR, may result in important knowledge in the field of targeting AR coregulators for new cancer therapeutics." (PMID 21935435, 2011). "Overexpressed AR may thus enable cancer cells to respond to low levels of androgen and to transduce signals sufficient for cell growth and survival." (PMID 24212771, 2011). "Are there cancer-specific modifications of such organization which might have anything to do with altered expression of AR-dependent genes?" (PMID 20406442, 2010). "While these cells are described as androgen-independent prostate cancer cells, they are generally considered as 'non-prostate-like cancer cells' mainly due the deficiency of androgen receptors (AR)." (PMID 20504375, 2010). "Early work on PNAs for cancer therapy showed that anti-sense PNAs directed against the androgen receptor and TATA-binding protein genes worked by hybridization with CAG triplet repeats in LNCaP and DU-145 cell lines; no binding to c-myc, which lacks the CAG repeats was observed." (PMID 21029412, 2010). "In PCa xenografts, an increase in AR mRNA and protein was both necessary and sufficient to convert growth from a hormone-sensitive to a hormone-refractory stage, while knocking down AR reduced cell growth in both androgen-sensitive and -insensitive cancer cells." (PMID 19691856, 2009). "To date, growing evidence suggests that genistein has the ability to inhibit cancer cell proliferation and induce cell apoptosis through regulation of biological molecules, such as the estrogen or androgen receptor, protein-tyrosine kinase, NF-kappa B, Akt and MAPK pathways." (PMID 19742137, 2009). "In contrast, 39% of poorly-differentiated carcinomas were ER-negative but AR-positive." (PMID 19405945, 2009). "The great majority of well-differentiated carcinomas were both AR and ER-positive." (PMID 19405945, 2009). "Furthermore, we observed strong correlation between Ebp1 expression and the nuclear expression of AR, Cyclin D1 and ErbB3 in both normal adjacent and cancer tissues." (PMID 19025630, 2008). "The observed high PRKCD mRNA levels in PCa metastases, which may reflect ligand-independent AR activation, possibly play a role in late stage disease because PRKCD is implicated in growth, migration and invasion of cancer cells, including PCa." (PMID 17553165, 2007). "The terms ‘androgen independent’ and ‘hormone refractory’ may be misnomers as the AR appears to maintain a role in cancer progression as demonstrated by its continued and even increased expression." (PMID 19675761, 2007). "To test the hypothesis that AR is not only expressed, but is still a key therapeutic target in advanced carcinomas, we injected siRNA targeting AR into mice bearing exponentially growing castration-resistant tumors." (PMID 17925854, 2007). "AR expression has been noted in some benign and malignant tumors." (PMID 17020615, 2006). "Similarly, IR could also be sufficient to induce a robust immune response via IRF3 phosphorylation downstream of dsRNA recognized by RIG-I/MDA5 in AR– cancers in which IKKε is readily expressed." (PMID 41542764, 2026). "Considering the obvious impact of the AR pathway on urothelial cancer cells, it is also tempting to speculate that higher androgen levels in males may contribute to the well-known gender disparity in this cancer type." (PMID 41463239, 2025). "Furthermore, this system is under direct transcriptional control by sex hormones: MBOAT1 is upregulated by the Estrogen Receptor (ER) and MBOAT2 by the Androgen Receptor (AR), directly linking sex-specific hormone signaling to ferroptosis resistance in relevant cancers." (PMID 41462611, 2025).
cancer (continued). "For example, androgen receptor (AR) variants that drive resistance to standard antagonists remain susceptible to degradation‐based strategies, and transcription factors such as STAT3—long considered among the most challenging cancer targets—are now tractable through systematic degradation." (PMID 41049269, 2025). "Such mutations may exacerbate male-predominant cancers by altering AR sensitivity in non-reproductive tissues." (PMID 41228208, 2025). "However, as the disease advances, cancer cells often develop mechanisms to bypass AR dependency." (PMID 40722714, 2025). "Moreover, the increased activation of androgen receptor expression in the PC cell lines and their surrounding tissues might be involved in the carcinogenesis and cancer development of PC and further lead to a higher burden of disease in males." (PMID 40519307, 2025). "Notably, lncRNAs like PCA3, HOTAIR, and CTBP1-AS are linked to AR pathway stimulation, with HOTAIR promoting cancer growth by directly interacting with AR, inhibiting its ubiquitination and degradation, and enhancing AR target gene expression independently of androgens." (PMID 40290121, 2025). "In addition to surgery, radiation therapy, and chemotherapy, there are 2 case reports describing the use of hormone therapy for patients with androgen receptor–positive cancer; 1 of these patients achieved long-term progression-free survival with hormone therapy alone." (PMID 40160875, 2025). "However, eventually, the cancer becomes castration resistant but still relies on AR signaling." (PMID 40072554, 2025). "The three different PCa cells, classified as AR-dependent or AR-independent, allowed us to assess the anti-cancer effect of compound 1 across various PCa phenotypes and determine whether 1 suppresses the PCa metastasis and proliferation via AR or other signalings." (PMID 40374533, 2025). "The results of this study indicate that the positive AR status in TNBC was associated with a lower recurrence and death hazard ratio during the 5-year follow-up, with a strong inverse correlation between AR expression and cancer cell proliferation (Ki-67 index)." (PMID 40150035, 2025). "Furthermore, the definition of TNBC using ER and PR protein expression (<1% versus <10%) may influence results, since it has been shown that AR inhibits cell proliferation in ER-expressing cancers through an ER signaling blockade." (PMID 40150035, 2025). "Additionally, increased the AR expression in RCC was reported to have repressed miR-143-3p, causing the loss of its regulatory effect on K-RAS, P-ERK, and AKT, the commonly activated pathways in cancer." (PMID 39585048, 2024). "However, cancer cells can have dysregulation of normal metabolic patterns and dysregulation of sex hormone receptor expression, and the impact of AR signaling on CD4+ T cell metabolism during inflammation is unknown." (PMID 39404231, 2024). "AZD5069 recognised by CXCR2 could improve the lack of the tumour suppressor phosatase and tensin homolog(PTEN), which can inhibit cancer cell survival through the inactivation of aldose reductase(AR), hypoxia induced factor‐1(HIF‐1) and nuclear factor‐kappa B(NF‐κB) transcription factors." (PMID 38450975, 2024). "ZIP synergy scores were obtained with the SynergyFinder software, and the scores for the HCC827/AR and H1975/AR cells were 14.228 and 13.987, respectively, indicating that almonertinib and baicalein had highly synergistic effects in suppressing cancer cell proliferation." (PMID 39144617, 2024). "Cancers that are AR-positive may depend on androgens for growth and progression." (PMID 38362126, 2024). "Relevant alterations range from genetic aberrations (e.g. AR-gain or mutations) to transcriptional changes such as alternative splicing (e.g. AR-V7), expression of PSMA and SLFN11, or upregulation of neuroendocrine markers (e.g. SYP, CHGA, NCAM1, and DLL3) in cancers cells." (PMID 39550585, 2024). "Thus, AR is an important drug target for AR-positive cancers." (PMID 39668349, 2024).
cancer (continued). "While most studies are performed to detect the AR-SVs focus on CRPCs, we focused on primary PCa with the assumption that expression of AR-SVs at an early stage might correlate with late-stage aggressive cancer." (PMID 36979627, 2023). "Thus, the androgen receptor role in cancer stem cells depends on the cellular context." (PMID 37894767, 2023). "The cancer trials utilize RNA‐knockdown ASOs targeted at oncogenes like B‐cell lymphoma 2 (NCT04072458) and genes associated with cancer cell growth and proliferation mediators like growth factor receptor‐bound protein 2 (NCT02781883 and NCT04196257) and androgen receptor (NCT03300505)." (PMID 36684099, 2023). "It has also been hypothesized to account for the phenotypic heterogeneity of AVPCs and the bidirectional transition of cancer cells between two morphologic and molecular states: AR-driven adenocarcinoma cells and AR-indifferent cells of small-cell and various other morphologies." (PMID 37686633, 2023). "Once AR binds to a ligand of interest, it will dissociate from the chaperone protein and will reconfigure into a homodimer that induces target gene transcription by translocating into the nucleus and activating a series of signaling events that lead to apoptosis escape and cancer cell proliferation." (PMID 37835396, 2023). "Methylation of the AR gene could lead to many diseases, e.g., cancer and developmental disorders." (PMID 36815184, 2023). "Therefore, our results on the downregulation of negative regulation of the androgen receptor suggests the high activity of AR during the progression of cancer that may be due to effect of miRNA regulation at mRNA level." (PMID 37925508, 2023). "In castration-resistant cancer cell lines, decreased tumor growth, increased apoptosis, altered lipidome, decreased lipid storage, and AR and AR-V7 expression have been observed after inhibiting FASN activity, thus highlighting the role that this enzyme may play in PCa progression." (PMID 36674430, 2023). "Therefore, the AR antagonism strategy has been highly efficient, as it can also affect the associated metabolic network; however, in the case of androgen-resistant PCa, androgen-independent AR activation takes place to bypass the AR requirement and become a more aggressive AR-indifferent carcinoma." (PMID 36901912, 2023). "Furthermore, AR activation can enhance the viability of cancer stem-like cells (CSCs) through an androgen paracrine action, and also facilitates the steaminess features of AR-positive cancer cells." (PMID 35960413, 2022). "Furthermore, dysregulation of the AR signaling axis could be involved in tumorigenesis of various types of cancers, including GBM." (PMID 36013056, 2022). "Therefore, it could be applied to develop new medicines or methods based on these studies to target AR or important factors in its related signaling pathways to control cancer development." (PMID 35886904, 2022). "The assessed prognostic and predictive value of AR/ER ratio in patients with primary HR+/HER2- BC treated with Tamoxifen suggested that this marker could be useful for prognostic classification of luminal cancers." (PMID 36111296, 2022). "Interestingly, cancer samples with an AR mutation (n = 101) had an overall higher total mutational burden than samples without an AR mutation (AR–, n = 96), 7.5 and 4.8 mutations on average, respectively (p < 0.001)." (PMID 35053623, 2022). "The expression of AR may be related to histological subtypes or staging of cancer." (PMID 35886904, 2022). "Thus, the expansion of the cancer stem cell subpopulation upon the induction of adaptive HIF signaling may also be conferring resistance to AR-targeted therapies." (PMID 36012111, 2022).